TIMP1 (TIMP metallopeptidase inhibitor 1)
Description:
Metalloproteinase inhibitor that functions by forming one to one complexes with target metalloproteinases, such as collagenases, and irreversibly inactivates them by binding to their catalytic zinc cofactor. Acts on MMP1, MMP2, MMP3, MMP7, MMP8, MMP9, MMP10, MMP11, MMP12, MMP13 and MMP16. Does not act on MMP14. Also functions as a growth factor that regulates cell differentiation, migration and cell death and activates cellular signaling cascades via CD63 and ITGB1. Plays a role in integrin signaling. Mediates erythropoiesis in vitro; but, unlike IL3, it is species-specific, stimulating the growth and differentiation of only human and murine erythroid progenitors.
Synonyms: EPA; TIMP-1; CLGI; TIMP; EPO; HCI
Tractability: Antibody: UniProt places it where antibodies can reach, with high confidence; its Gene Ontology location is reachable by antibodies, with high confidence; UniProt predicts a signal peptide or a membrane-spanning region. PROTAC: ubiquitination databases record sites on it.
Gene: Protein-coding gene on chromosome X (47,582,408 to 47,586,789, forward strand). Ensembl gene ENSG00000102265.
Subcellular location: Secreted
Subcellular location (Human Protein Atlas): Golgi apparatus; Vesicles; Predicted to be secreted
Pathways (Reactome):
Immune System: Interleukin-10 signaling; Interleukin-4 and Interleukin-13 signaling
Metabolism of proteins: Post-translational protein phosphorylation; Regulation of Insulin-like Growth Factor (IGF) transport and uptake by Insulin-like Growth Factor Binding Proteins (IGFBPs)
Extracellular matrix organization: Activation of Matrix Metalloproteinases
Hemostasis: Platelet degranulation
Signal Transduction: TGFBR3 PTM regulation
Gene Ontology:
Molecular function: cytokine activity; metalloendopeptidase inhibitor activity; peptidase inhibitor activity; protein binding; zinc ion binding; protease binding
Biological process: cellular response to UV-A; negative regulation of catalytic activity; negative regulation of endopeptidase activity; negative regulation of membrane protein ectodomain proteolysis; negative regulation of metallopeptidase activity; negative regulation of trophoblast cell migration; positive regulation of cell population proliferation; regulation of integrin-mediated signaling pathway; response to cytokine; response to hormone; cartilage development; cellular response to acetaldehyde; cellular response to peptide; negative regulation of apoptotic process; negative regulation of proteolysis; response to peptide hormone; signal transduction
Cellular component: extracellular exosome; extracellular region; endoplasmic reticulum lumen; extracellular matrix; platelet alpha granule lumen; basement membrane; secretory granule lumen
Homologues: Orthologues: chimpanzee TIMP1 (100% identical), macaque TIMP1 (98% identical), pig TIMP1 (84% identical), dog TIMP1 (81% identical), rabbit TIMP1 (81% identical), guinea pig TIMP1 (73% identical), mouse Timp1 (72% identical), rat Timp1 (71% identical). Paralogues in human: TIMP2 (40% identical), TIMP3 (37% identical), TIMP4 (35% identical).
Diseases named in the same sentence as TIMP1 in open-access papers:
TIMP1 is named in the same sentence as 669 diseases in open-access papers, as found by Europe PMC text mining. Sharing a sentence is not in itself a finding about the gene and the disease. The quoted sentences say what the papers report.
liver fibrosis (406 papers, 2009 to 2026). "Circulating biomarkers that are associated with liver fibrosis hyaluronic acid was significantly elevated in the obese group, while galectin-3 and tissue inhibitor of metalloproteinase (TIMP)-1 were comparable in both groups." (PMID 40806703, 2025). "The activation of the TGF-β/SMAD signaling pathway in HSCs resulted in the upregulation of several key genes associated with hepatic fibrosis, including TIMP1, SMAD2, SMAD3, COL1A1, and MMP2, as well as increased secretion of MMP-9 protein." (PMID 39201682, 2024). "It has been shown that serum TIMP-1 levels increase in patients with chronic liver disease, which is associated with the histological grade of liver fibrosis." (PMID 36110559, 2022). "TIMP-1, a tissue inhibitor of matrix metalloproteinase with strong activity, is associated with liver fibrosis." (PMID 36569295, 2022). "IL-5 produced by lung-derived ILC2s can drive eosinophilia while IL-13 can stimulate hepatic stellate cells and induce upregulation of fibrosis-associated genes including Col1a1, Acta2 and Timp1, thus promoting liver fibrosis." (PMID 34305911, 2021). "In an experimental model of liver fibrosis, increased activity of TIMP-1 was found to be associated with a decreased spontaneous hepatic fibrosis resolution." (PMID 34957156, 2021). "In TAA-induced liver fibrosis, the CD1d deficient mice show ameliorated liver fibrogenesis with blunted TIMP-1 expression, whereas in CCl4-induced liver fibrosis, NKT-deficient mice are more susceptible." (PMID 32676074, 2020). "The expression of COL1A2, COL3, and TIMP-1 mRNA, which encode proteins involved in hepatic fibrosis, was analyzed." (PMID 30673721, 2019). "The European Liver Fibrosis study compared the diagnostic performance of HA, PIIINP and TIMP-1 with liver biopsy with threshold sensitivity greater than 90% and specificity greater than 90% can detect liver fibrosis." (PMID 29255622, 2018). "Over expression of TIMP-1 is associated whit liver fibrosis, while MMP-13 cleaves and inactivates CCL2, CCL7 and CXCL12 leading to reduction in chemotaxis, as well as to a decrease in the fibrosis process." (PMID 29040281, 2017). "In contrast, another study demonstrated increased carbon tetrachloride (CCl4)-induced liver fibrosis in TIMP-1 deficient mice." (PMID 28386095, 2017). "Contrasting these data that suggest profibrogenic functions for TIMP-1, a recent study found that TIMP-1-deficient mice were even more susceptible to CCl4-induced liver fibrosis than wild type mice." (PMID 28386095, 2017). "This included genes associated with metabolism (Fabp1, Insr), genes associated with cell stress (Atf6, Ddit3, and Eif2ak3), genes associated with liver fibrosis (Hgf, Sp1, and Timp1) and genes associated with the inflammatory response (Tnf, Ptpn22, and Pparg)." (PMID 28686204, 2017). "Second, many markers seemed to be related to liver fibrosis progression, but with different association patterns in the two cohorts: TIMP-1 levels were associated with fibrosis progression in the pediatric cohort and HA, PIIINP and TGF-ß1 in adults." (PMID 21858035, 2011). "It is evident that in experimentally induced liver fibrosis in rodents, cessation of liver injury results in fibrosis regression, usually associated with reduction of TIMP-1 expression and HSC apoptosis." (PMID 19183465, 2009). "Moreover, TIMP1, which is associated with increased risk of liver fibrosis, was found to be lower in women compared to men, and a similar sex difference was found for PAI-1." (PMID 40806703, 2025). "HA, together with procollagen III N-terminal peptide (PIIINP) and tissue inhibitor of metalloproteinase 1 (TIMP1), is used to calculate the enhanced liver fibrosis (ELF) score, a non-invasive diagnostic tool for detectingsevere fibrosis in patients with chronic hepatitis B, hepatitis C, and HIV." (PMID 40475534, 2025).
liver fibrosis (continued). "Additionally, the expression of tissue inhibitors of metalloproteinases (TIMPs), such as TIMP1, has been implicated in liver fibrosis progression." (PMID 40964049, 2025). "Indeed, PIIINP concentrations seem to increase in response to collagen deposition during fibrosis, and TIMP-1 has been implicated in the progression to hepatic fibrosis." (PMID 39598344, 2024). "Subsequently, transcript levels of genes associated with hepatic fibrosis were assessed via qRT-PCR, which revealed a significant upregulation of fibrosis-related transcripts encoding proteins such as procollagen α1(I), TIMP-1, α-SMA (ACTA2), MMP-2, and MMP-9 in the livers of scurfy mice." (PMID 37818371, 2023). "The increase of CCl4-induced reactive oxygen species may cause tissue damage through lipid peroxidation, increase the expression of the tissue inhibitor of metalloproteinase-1 (TIMP-1), and cause liver fibrosis due to the accumulation of collagen in the liver." (PMID 35721129, 2022). "In addition, western blot and qRT-PCR analysis showed that deficiency of Airn significantly promoted the upregulation of CCl4-induced α-SMA, COL1α1, MMP2, and TIMP1, suggesting Airn deficiency aggravated CCl4-induced liver fibrosis." (PMID 36171606, 2022). "However, even when we combined the genotoxic carcinogen DEN with induction of liver fibrosis by CCl4, liver tumor growth in TIMP-1-deficient mice and their wild type littermates was similar." (PMID 28386095, 2017). "The increase in TIMP1 observed at the latest time point mirrors the clinical situation where elevated levels are associated with hepatic fibrosis due to schistosomiasis japonica in supernatents of patient PBMCs (peripheral blood mononuclear cells) stimulated with schistosome egg antigen." (PMID 25965781, 2015). "However, recent studies have reported that MMP-2-deficient animals show increased liver fibrosis, due to increased collagen I synthesis and suppressed TIMP-1 upregulation." (PMID 23056273, 2012). "Therefore, TIMP-1 upregulation is often considered a risk factor for liver fibrosis." (PMID 39937012, 2025). "Thus, TIMP-1 harbors functions that might contribute to both, hepatic fibrogenesis and carcinogenesis, and has been epidemiologically associated with liver fibrosis and HCC." (PMID 28386095, 2017). "Taken together, we demonstrate for the first time that SHBG protects against liver fibrosis by promoting collagen degradation via the TGF-β1/MMPs/TIMP1 pathway." (PMID 42278422, 2026). "In TSNO mice, CA markedly enhanced hepatic fibrosis, increased Col1a1 and Timp1 expressions, and promoted CD11c+ monocyte-derived macrophage infiltration." (PMID 41751341, 2026). "TIMP1+ LSECs promote the recruitment of CD63+ monocyte-derived macrophages (MoMFs) during liver fibrosis progression." (PMID 41842990, 2026). "OATD-01 and ALK5i demonstrated efficacy in parameters such as serum biomarkers – AspAT, as well as biomarkers from ELF panel (enhanced liver fibrosis – measured serum levels of procollagen 1, TIMP-1 and hyaluronian)." (PMID 40510344, 2025). "In the present study, after DMDD treatment, hepatic TGF-β, Smad2, and Smad3 were significantly downregulated, and COL1A1, α-SMA, and TIMP1 were key genes in liver fibrosis." (PMID 40453659, 2025). "Collagen proportionate area (CPA), hydroxyproline quantification, and assessment of fibrogenic gene expression (Acta2, Col1a, Tgfb1, and Timp1) showed a minor effect of Prdx2 KO on liver fibrosis." (PMID 40932790, 2025). "Meanwhile, EGCG can also downregulate liver fibrosis-associated TGF-β/SMAD and PI3K/Akt/FoxO1 signaling and the expression of collagen I-α1, tissue inhibitor of metalloproteinase 1 (TIMP-1), and α-smooth muscle actin (a-SMA)." (PMID 40218859, 2025). "PZW mitigated hepatic fibrosis in association with IL-6/JAK2/STAT3 and TGF-β/Smad2/3 signaling pathway inhibition favoring MMP1/TIMP-1 ratio that attenuated collagen deposition and promoted collagen degradation." (PMID 41293246, 2025).
liver fibrosis (continued). "A previous study revealed that silencing of Timp1 attenuates HSCs proliferation suggesting the central role of TIMP-1 in liver fibrosis." (PMID 40486848, 2025). "PZW mitigated hepatic fibrosis, with its effect associated with the inhibition of the IL-6/JAK2/STAT3 and TGF-β/Smad2/3 signaling pathways and through raising the MMP1/TIMP-1 ratio." (PMID 41293246, 2025). "qPCR analysis revealed an upregulation of tissue inhibitor of metalloproteinase-1 (TIMP-1), a known matrix metalloproteinase inhibitor, in the liver fibrosis tissues." (PMID 40822973, 2025). "Identifying TIMP1 as a potential driver of liver fibrosis in HBV-infected mice highlights the complexity of host-virus interactions." (PMID 40964049, 2025). "Current research on the relationship between TIMP1 and ferroptosis primarily focuses on areas such as liver fibrosis and ulcerative colitis." (PMID 40687427, 2025). "This diagnostic tool estimates the severity of liver fibrosis by measuring hyaluronic acid, procollagen III amino-terminal peptide (PIIINP), and TIMP-1—serum markers of changes occurring in the extracellular matrix during the fibrogenesis process." (PMID 41302136, 2025). "The increased expression of TIMP1 is particularly notable, as TIMP1 is a key regulator of extracellular matrix remodeling and liver fibrosis progression." (PMID 40964049, 2025). "In hepatic fibrosis, TIMP-1 inhibits the matrix metalloproteases (MMP), which can prevent fibrosis by the degradation of ECM." (PMID 38338453, 2024). "The enhanced liver fibrosis (ELF) score is a blood test that combines tissue inhibitor of metalloproteinases 1 (TIMP-1), amino-terminal propeptide of type III procollagen (PIIINP), and hyaluronic acid (HA)." (PMID 39001207, 2024). "The ability of PAC to downregulate the expressions of collagen-1, α-SMA, and TIMP-1 in the HSC is beneficial to prevent hepatic fibrosis by inhibiting excessive ECM secretion." (PMID 38338453, 2024). "Collagen 1a1 and TIMP1 were significantly upregulated in CYP/DKOAbcb4-deficient mice, suggesting the importance of hydrophobic bile acid composition in liver fibrosis." (PMID 39111549, 2024). "Except for TIMP1, noninvasive liver fibrosis markers had generally increased from baseline to weeks 4 and 8 (30–60 mg QD dosing period), before declining to near baseline levels at week 12 (100 mg QD dosing period)." (PMID 38976363, 2024). "Similar to our results, upregulation of MMP2 and MMP14 together with upregulation of TIMP1 has been shown in liver fibrosis." (PMID 38990974, 2024). "Increased IL-1β secretion upregulates TIMP-1, inhibiting extracellular matrix degradation and fibroblast apoptosis and aggravating liver fibrosis." (PMID 38595921, 2024). "An experimental animal study documented attenuation of liver fibrosis upon treatment with anti-TIMP-1 antibody." (PMID 39201329, 2024). "Another study found that the injection of HSYA into Sprague Dawley rats regulated gene expressions of MMP-9 and TIMP-1 to reduce liver fibrosis in chronic liver disease." (PMID 39062816, 2024). "Liver fibrosis improved in all patients, with significant declines in TIMP-1 levels, LSM, and FIB-4 score." (PMID 39459866, 2024). "Col1A1, Timp1, and Tgfβ1, which are commonly regarded as fibrosis markers, were upregulated in liver fibrosis." (PMID 38372748, 2024). "TIMP1, a known marker of liver fibrosis, was highly induced in mesenchymal cells after hepatic injury." (PMID 39699962, 2024). "Higher levels of liver and serum TIMP-1 have been found in patients as well as in animal models of liver fibrosis." (PMID 39201329, 2024). "The observed imeglimin-mediated attenuation of hepatic fibrosis coincided with decreased hepatic expression levels of genes related to fibrogenesis, including Timp1, Ctgf, and Tgfb1." (PMID 39594556, 2024). "PIIINP and TIMP-1 have been involved in the fibrogenesis, being potentially predictors of hepatic fibrosis." (PMID 39598344, 2024).
liver fibrosis (continued). "To date, TIMP1 has shown moderate performance for diagnosing hepatic fibrosis (AUROC of 0.74), while it has a much higher accuracy for discriminating steatohepatitis with an AUROC of 0.97, 97% sensitivity and 100% specificity." (PMID 38809396, 2024). "Treatment with α4β7 mAb reduced hepatic fibrosis reflected by decreased collagen deposition in the liver and significant reduction in the transcript levels of Acta2, Col1a1, Col1a2, Tgfb1 and Timp1." (PMID 38727292, 2024). "This is evidenced by the observed suppression of established hepatic fibrosis markers, including type I and IV collagen, TIMP-1, and MMPs (MMP-2 and MMP-9)." (PMID 39201682, 2024). "The ELF panel is an algorithm developed by the European Liver Fibrosis Group based on the analysis of HA, TIMP-1, and PIIIPN." (PMID 39201990, 2024). "SOD-1 knockout mice were shown to cause liver fibrosis by promoting MMP (MMP 2 and 9) and TIMP (TIMP1) protein expression; collagen accumulated in the liver." (PMID 37298640, 2023). "Conversely, TIMP1 was reduced, suggesting that the lost balance between MMP-9 and TIMP1 can contribute to the protective effects of SME against liver fibrosis." (PMID 38001866, 2023). "In mice treated with ethanol and CCl4, down-regulation of TIMP1 effectively inhibited hepatic fibrosis and activation of hepatic stellate cell." (PMID 37090703, 2023). "It should be noted that the effective usage of Timp1-targeted constructions, such as siRNA and shRNA, for the treatment of liver fibrosis and other diseases accompanied by an imbalance in the synthesis/degradation of ECM components, such as keloids, was shown." (PMID 36675165, 2023). "It is worth noting that gelatinases such as MMP-9 are also considered potential targets for the treatment of liver fibrosis and hepatic repair as they scavenge TIMP-1 and are responsible for collagen degradation." (PMID 36978885, 2023). "We reported that hepatocytes extracted exosomes treated with H. pylori-derived OMVs can cause HSC activation and elevate the expression of hepatic fibrosis markers (β-catenin, vimentin, α-SMA, and TIMP-1)." (PMID 37090196, 2023). "TIMP1 has also been suggested as a promoter of hepatic fibrosis through the inhibition of matrix degradation." (PMID 36768808, 2023). "TIMP-1 was upregulated during liver fibrosis and is thought to promote fibrosis in the damaged liver by inhibiting MMP and ECM degradation." (PMID 36816804, 2023). "Pre-symptomatic results from carbon tetrachloride-induced hepatic fibrosis in rat models treated with anti-TIMP1 antibody revealed accumulation of fibrosis, decreased HSC activation, as well as reduced MMP2 activity." (PMID 36985782, 2023). "As the damage was stopped, TIMP-1 levels decreased, according to several studies on the treatment of hepatic fibrosis in rats." (PMID 36985782, 2023). "Gene expression of Col1a1, TGFβ-1, TIMP-1, MMP-2, and MMP-9, which are associated with liver fibrosis, was significantly higher in MCDHFD mice than in control animals." (PMID 37107346, 2023). "TIMP-1, upregulated in liver fibrosis development both in murine experimental models and human samples, is a significant contributor to greater morbidity and poor prognosis in HF." (PMID 36816804, 2023). "In the current study, we found that exosomes from infected hepatocytes with H. pylori OMVs promote HSC activation via elevated β-catenin, α-SMA, and TIMP1 protein levels and downregulated e-cadherin proteins which revealed the hepatic fibrosis." (PMID 35832384, 2022). "Consistent with the results of the present study, several studies have shown that TIMP-1 in hepatic fibrosis increases in both mouse and human models and promotes the development of hepatic fibrosis." (PMID 36110559, 2022). "Along with this, the mRNA levels of several liver fibrosis-related genes (Col1a1, Mmp9, Timp1) were also increased in livers from Gm4951−/− mice." (PMID 35842425, 2022).